LCN2 (lipocalin 2)
Diseases named in the same sentence as LCN2 in open-access papers (continued):
Sharing a sentence is not in itself a finding about the gene and the disease.
cardiovascular disease (66 papers, 2010 to 2025). "Elevated circulating hsCRP and pro-inflammatory adipocytokines like FABP4, leptin and lipocalin-2 increase the risk for cardiovascular disease by not only endocrine but also paracrine mechanisms." (PMID 30395653, 2018). "Therefore, future studies including detailed associations between LCN2 and metabolic or other cardiovascular disease risk parameters will be relevant to determine the use of this adipokine in the context of RA." (PMID 39403549, 2024). "Furthermore, elevated circulating LCN2 levels have been linked to an increased risk of cardiovascular disease." (PMID 36974345, 2023). "Recent research on LCN2 in clinical trials has mainly focused on patients with cardiovascular diseases comorbid with depressive disorders." (PMID 38589429, 2024). "Amongst other immune cells, neutrophils play a key role in systemic inflammation leading to cardiovascular disease and can release inflammatory factors, including lipocalin-2 (LCN2)." (PMID 33603000, 2021). "Collectively, LCN2 enhancement in cardiovascular disorders, especially in the deamidated form, seems to accelerate CVD progression." (PMID 32544571, 2020). "Despite a wide literature supporting a role of LCN2 in the pathophysiology of cardiovascular disease, to date there are insufficient data regarding the clinical usefulness of monitoring LCN2 concentrations in the treatment of cardiovascular diseases." (PMID 33192583, 2020). "Increasing evidences suggest the involvement of LCN2 in inflammatory processes in cardiovascular diseases." (PMID 33192583, 2020). "LCN2 also contributes to a range of cardiovascular diseases by activating ferroptosis processes." (PMID 39613734, 2024). "However, the role of LCN2 in calcification-related cardiovascular diseases has been investigated in only a few studies." (PMID 39613734, 2024). "LCN2 plays a role in transportation of small hydrophobic molecules such as lipids, steroid hormones and retinoids; furthermore LCN2 is a candidate cardiovascular disease gene and may function as a modulator of inflammation." (PMID 34745199, 2021). "Among the 10 cardiovascular disease markers tested, 7 showed significant differences between groups (D-dimer, GDF-15, myoglobin, sICAM-1, MPO, P-selectin and lipocalin-2/NGAL)." (PMID 36163447, 2022). "By analysing plasma samples of patients with angiographically documented CAD, we confirmed its potential role as a marker for cardiovascular disease as well as its correlation with the severity of CAD, which may be in part driven by LCN2-activated macrophages." (PMID 26367277, 2015).
metabolic disorders (60 papers, 2012 to 2026). "In the liver, LCN2 is primarily associated with inflammatory processes and is considered a potential biomarker in metabolic disorders." (PMID 41677583, 2026). "Notably, LCN2 is a neutrophil gelatinase-associated lipocalin, and has been reported to act as a pleiotropic mediator in several inflammatory and metabolic diseases." (PMID 36973755, 2023). "Lcn2 gene encodes Lipocalin-2 which plays a pro-inflammatory role in metabolic diseases." (PMID 35844518, 2022). "LCN2 exhibits a dual role in metabolic disorders, with studies suggesting different functions for the molecule during inflammation." (PMID 40951890, 2025). "For example, Lcn2, also referred to as neutrophil gelatinase-associated lipocalin (NGAL), has been well-investigated in metabolic disorders, and is characterized as a critical pro-inflammatory mediator during inflammation-associated diseases." (PMID 35757735, 2022). "Recently, we and others have shown the protective function of Lcn2 during acute and chronic inflammatory and metabolic disorders in mice." (PMID 32883997, 2020). "LCN2, a bone and adipose-derived hormone, is associated with increased cardio-metabolic disease risk, however, differences across the lifespan have not been well characterized." (PMID 39830147, 2025). "Additional research suggests that various other adipocytokines, including retinol-binding protein 4 (RBP4), lipocalin-2, omentin-1, vaspina, and others, might serve as potential biomarkers for assessing metabolic disorders." (PMID 40310144, 2025). "A recent study showed that blood SCFA levels are directly linked to health maintenance during MS and metabolic diseases; therefore, we examined the association between serum SCFA levels and underlying MS-linked intestinal inflammatory activity using Lcn-2 as a readout." (PMID 36341389, 2022). "Interestingly, the level of fecal SCFAs was increased in the MS Lcn-2-high participants as observed in metabolic diseases." (PMID 36341389, 2022). "This suggests that LCN2 plays an important role in metabolic disease." (PMID 34903175, 2021). "In addition to its inflammatory role in CVD, LCN2 regulates chronic inflammation in other metabolic disorders." (PMID 32544571, 2020). "LCN2 has been investigated as a therapeutic target in cardiovascular and metabolic disease, but no LCN2-directed therapies have reached clinical approval." (PMID 41303567, 2025). "Unlike LCN2 roles in metabolic disorders, mechanistic studies conducted on LCN2-KO mice have demonstrated possible cause–effect relationships between LCN2 and the development of atherosclerotic disease." (PMID 32544571, 2020). "However, their distinct correlations with various metabolic parameters, suggest that lipocalin-2 and RBP4 should have different patterns of regulation and there exists a complex interconnection between these two lipocalin proteins and metabolic disorders." (PMID 23799122, 2013).
inflammation (30 papers, 2012 to 2026). Aberrant reaction of the microcirculation characterized by movement of fluid and leukocytes from the blood into extravascular tissues. "We analyzed the systemic level of LCN2 associated with chronic cervical inflammation during HPV infection as a potential biomarker to identify patients with a different CC stage." (PMID 31151292, 2019). "For instance, a large number of NE1 cells were expressed with mature neutrophil markers (e.g., Retnlg, Lcn2, and Asprv1, associated with chronic inflammation), while NE2 cells were highly expressed with pro-inflammatory molecules (e.g., Tnf, Il1b, and Nlrp3, which trigger acute inflammation)." (PMID 37781362, 2023). "Studies have shown that LCN-2 expression is increased in patients with intestinal inflammatory disorders, and its levels were significantly associated with the degree of severity of gut inflammation." (PMID 38071298, 2023). "Several genes that are involved in mucosal protection and immunity, such as Cxcl2 and IL-12A, retain levels of expression that are comparable to those observed in WT C57BL/6 mice and Lcn2, a gene that has been associated with gut inflammation, was detected at higher levels in Casp1−/− mice." (PMID 23977202, 2013). "We also identified additional FGF23-responsive transcripts and activation of networks associated with renal damage and chronic inflammation, including lipocalin 2 (Lcn2), transforming growth factor beta (TGF-β) and tumor necrosis factor-alpha (TNF-α) signaling pathways." (PMID 22970174, 2012). "We also showed that the mouse cathelicidin peptide CRAMP (mouse orthologue of LL-37) negatively correlates with LCN-2 and neutrophil elastase (NE) in an IL-17-driven mouse model of airway inflammation." (PMID 40410820, 2025). "During IBD and other forms of intestinal inflammation, upregulated Lcn2 production prevents the outgrowth of Ent-dependent microbes." (PMID 36094114, 2022). "Studies also revealed the association of lipocalin-2 (LCN2) and low-density lipoprotein receptor-related protein-1 (LRP1) with intestinal inflammation." (PMID 34423140, 2021). "Lipocalin-2 (LCN2) indicates an early biomarker of the liver inflammation, and its values are in correlation with the degree of the liver damage." (PMID 31590249, 2019). "In our previous publication, we reported that the systemic level of LCN2 was associated with chronic cervical inflammation during HPV infection, and our data supported the hypothesis that LCN2 might be important in the oncogenesis of CC." (PMID 38541074, 2024). "Increased Lcn2 expression was also detected upon BLM-induced pulmonary inflammation and fibrosis, especially at the acute phase correlating with neutrophilic infiltration, as well as upon LPS-induced ALI, an animal model characterized by neutrophilic infiltration." (PMID 37746070, 2023). "To further characterise DSS- and/or P-induced intestinal inflammation, we analysed micro-DAI, immune cell infiltration in the distal colon, release of a marker of intestinal injury (faecal concentration of Lcn-2 for neutrophil gelatinase-associated Lcn), and colonic inflammation (colon length)." (PMID 36687706, 2022). "Thus, serum Lcn2 levels were distinctly elevated only when higher degrees of gut inflammation coexisted with spinal ankylosis, as was present only in the ank/ank mice." (PMID 32188494, 2020). "To test for a possible overlap between LCN2 and AimA function, we asked whether addition of mLCN2 to a model of soysaponin-induced intestinal inflammation would alter AimA’s efficacy." (PMID 30398151, 2018). "Thus, our data suggest that LCN2-mediated activated macrophages could play an important role in the regulation of acute lung inflammation." (PMID 36923935, 2023). "Using a murine model of airway inflammation, we demonstrated enhancement of IL-17A/F, TNF-α, LCN-2 and neutrophil chemokine KC in the lungs, thus corroborating our findings in-vivo." (PMID 36517803, 2022).
neurological diseases (25 papers, 2014 to 2026). "Even though LCN2 has been extensively studied in a broad range of neurological disorders, the exact mechanisms underlying different functions of LCN2 are still not fully understood, which emphasizes the need for more research in this field." (PMID 41487016, 2026). "For neurological diseases, the role of LCN2 has been implicated in diabetic encephalopathy and some other neurological diseases in animal models with metabolic disturbance." (PMID 34636748, 2021). "Among these genes, Ch25h, Trpa1, Cdkn1a, Ly6g6e, Six3, and Opalin are potentially associated with neurological diseases; Lcn2, Serpina3f, Lao1, Trim29, bcl3, and Gkn3 are associated with inflammatory response." (PMID 30804943, 2019). "Lcn2 is implicated in the pathophysiology of different neurological disorders." (PMID 39110292, 2024). "Lipocalin‐2 (LCN2) has been implicated in promoting apoptosis and neuroinflammation in neurological disorders; however, its role in neural transplantation remains unknown." (PMID 33421207, 2021). "In addition, the expression level of LCN2 may serve as a diagnostic indicator for certain neurological disorders and as a monitor of treatment efficacy." (PMID 40182140, 2025). "Further studies on the functions and mechanisms of LCN2 can help to reveal the pathogenesis of neurological diseases and provide new targets and strategies for their treatment." (PMID 40182140, 2025). "Pharmacological targeting of Lcn2 has emerged as a potential therapeutic strategy in neurological disorders." (PMID 41294825, 2025). "Studies have demonstrated that LCN2 regulates the immune and inflammatory responses in a range of neurological diseases." (PMID 38991663, 2024). "The newly discovered protein target, LCN2, warrants further investigation to elucidate its specific mechanisms of action in neurological diseases." (PMID 39113712, 2024). "This study has elucidated the pivotal function of Lcn2 in TBI using experimental methods, which aligns with previous research findings emphasizing the involvement of Lcn2 in various neurological disorders." (PMID 39110292, 2024). "Specifically, 2-DG reduced the expression of the inflammatory genes C3, TNFα, LCN2, and IL6, all of which are implicated in various neurodegenerative and neurological diseases." (PMID 35326266, 2022). "A variety of studies have demonstrated that LCN2 is broadly expressed in many tissues such as the adipose tissue, liver, kidneys, lungs, and the brain and serves roles in both metabolic and neurological disorders." (PMID 34636748, 2021). "As a result of its active participation in the pathogenesis of various neurological diseases, LCN2 can be considered a promising therapeutic target for both prognostic and diagnostic purposes." (PMID 33613327, 2021). "Overall, these insights suggest that targeting LCN2 could offer a promising therapeutic strategy for mitigating neuroinflammation in a range of neurological disorders." (PMID 41487016, 2026). "Collectively, these findings establish LCN2 as a pleiotropic mediator of neuroinflammatory pathogenesis across neurological disorders, positioning pharmacological modulation of LCN2 expression or ligand-receptor interactions as a therapeutic target for CNS conditions." (PMID 40307216, 2025). "LCN2 has been reported to be related to various neurological diseases." (PMID 38589429, 2024). "However, although we found association between LCN2 and vascular disruption in neonatal mice, further studies are required to better delineate the pathophysiological involvement of LCN2 in the vascular changes and neurological disease." (PMID 37496672, 2023). "Although further detailed investigation may be required, a method to reduce LCN2 levels in astroglial-enriched cells will provide insights into how to reduce reactive-astrocyte-induced neurotoxicity in various neurological disorders." (PMID 37958847, 2023).
neurological diseases (continued). "Recently, multiple bone-derived modulators have been shown to participate in brain function and neurological disorders, including osteocalcin, lipocalin 2, and osteopontin, as have bone marrow-derived cells such as mesenchymal stem cells, hematopoietic stem cells, and microglia-like cells." (PMID 34179014, 2021). "Notably, the involvement of LCN2 has recently been implied in the neurological disorders from the studies in diabetic rodent models." (PMID 34636748, 2021). "LCN2 is a regulator of immune and inflammatory responses in a range of neurological diseases." (PMID 30761088, 2019). "Lipocalin-2 (LCN2) is an acute phase protein known to promote neuroinflammation via the recruitment and activation of immune cells and glia, particularly microglia and astrocytes, thereby inducing proinflammatory mediators in a range of neurological disorders." (PMID 30761088, 2019). "Therefore, pharmaceutical approaches targeting LCN2 in neurological diseases have emerged and regulating LCN2 levels may become an important therapeutic approach for various neurological disorders." (PMID 37958847, 2023). "The study highlights the upregulation of lipocalin-2 (LCN2), a protein typically elevated in neurological diseases, suggesting its potential as a therapeutic target." (PMID 39113712, 2024). "Among them, LCN2, TIMP1, S100A8/9, and PRDX2 related to host response and/or inflammation in neurological disorders, could be used as potential biomarkers of brain pathology." (PMID 24695528, 2014). "However, despite no detection of LCN2 in the neurons of LCN2-KO mice, we speculate that Dnaja3 is likely an important mediator of LCN2-induced apoptosis in nervous system diseases." (PMID 34903175, 2021).
neurodegenerative disease (21 papers, 2014 to 2025). A disorder of the central nervous system characterized by gradual and progressive loss of neural tissue and neurologic function. "LCN2 seems to be associated with many neurodegenerative diseases, and there is evidence to suggest that LCN2 can participate in the pathophysiology of neurodegenerative diseases by affecting pathways such as inflammation, cell death/survival signaling, and iron metabolism." (PMID 41018204, 2025). "Therefore, measuring the level of LCN2 secreted by activated astrocytes, potentially in the blood plasma and urine, may serve as an early indicator of and diagnostic tool for neurodegenerative diseases." (PMID 37779143, 2023). "Research has identified elevated levels of LCN2 in CSF as a marker that helps distinguish AD from other neurodegenerative diseases, correlating with CSF amyloid-β42 levels." (PMID 40153574, 2025). "By intervening in astrocytes, the expression, and secretion of Lcn-2, and their interactions, it is possible to effectively suppress the progression of neuroinflammation and yield positive outcomes in the treatment of neurodegenerative diseases." (PMID 38533497, 2024). "S100β, in combination with the complement protein C3, is a marker for reactive astrocytes in prion and other neurodegenerative diseases, as is lipocalin 2 (LCN2) in combination with C3." (PMID 38786054, 2024). "Future research should continue to explore the molecular interactions and signaling pathways related to Lcn-2 and neuroinflammation, to better understand its role in neurodegenerative diseases." (PMID 38533497, 2024). "Through the efforts of multidisciplinary cooperation, Lcn-2 is expected to become an important target for the treatment of neurodegenerative diseases in the future, bringing better quality of life and treatment outcomes for patients." (PMID 38533497, 2024). "Given the similarities in pathology between brain injury and CM development, in addition to the potential role of LCN2 in BBB breakdown and neurodegenerative diseases, the use of LCN2 as a marker for CM is promising." (PMID 36844403, 2023). "Characterized as an inflammatory protein and iron regulator, LCN2 is deemed as a new biomarker in neurodegenerative diseases." (PMID 32153594, 2020). "LCN2, a secreted glycoprotein in the lipocalin superfamily, has been reported to play a harmful role in ischaemic brains and neurodegenerative diseases." (PMID 31565154, 2019). "For example, Lcn2, one of the most up-regulated genes, given its features as an iron regulator and inflammatory protein in the CNS, has emerged as a new player in neurodegenerative diseases." (PMID 30804943, 2019). "Neuroinflammation due to brain injury or neurodegenerative diseases initiates the secretion of LCN2 from astrocytes, microglia, endothelial cells, and neurons." (PMID 31565154, 2019). "Lipocalin-2 (LCN2), a secreted glycoprotein belonging to the lipocalin superfamily, has been reported to play a detrimental role in ischaemic brains and neurodegenerative diseases." (PMID 31565154, 2019). "Neurodegenerative diseases are characterized by a glial reaction and LCN2 has been shown to be secreted by reactive astrocytes as a neurotoxic mediator leading to neuron death." (PMID 24695528, 2014). "Lcn-2 affects astrocytes in various neuroinflammatory and neurodegenerative diseases." (PMID 38533497, 2024). "Astrocyte-secreted protein Lipocalin-2 (LCN2) may hold the key to preventing neurodegenerative diseases, according to a new study." (PMID 37779143, 2023). "Furthermore, manipulating the activated state of astrocytes by reducing LCN2 levels is a potential therapeutic strategy for overcoming neurodegenerative diseases." (PMID 37779143, 2023). "Therefore, LCN2 secreted from activated astrocytes is a promising biomarker for the early prediction, diagnosis, and inhibition of the progression of neurodegenerative diseases." (PMID 37779143, 2023).